IL10 (interleukin 10)
Diseases named in the same sentence as IL10 in open-access papers (continued):
Sharing a sentence is not in itself a finding about the gene and the disease.
toxoplasmosis (37 papers, 2007 to 2025). A parasitic disease contracted by the ingestion or fetal transmission of toxoplasma gondii. "Associated with increased pro-inflammatory cytokines during toxoplasmosis, IL-10 plays a central role in reducing inflammation and severe immunopathology mediated by CD4+ T cells." (PMID 34683874, 2021). "Given that effector T cells from Pilrb−/− mice have an increased propensity for secreting IL-10, we assessed the production of IL-27 in WT and Pilrb deficient mice after i.p infection as a potential mechanism for the enhanced resistance to toxoplasmosis." (PMID 22479310, 2012). "Therefore, IL-10 is critical for establishing a chronic toxoplasmosis phase, associated with formation of T. gondii type II strains." (PMID 33912181, 2021). "Thus, the notably increased levels of IL-10 and IL-4 in this work could be beneficial to prevent excessive Th1-type responses from causing pathological damage to mice and in combating toxoplasmosis." (PMID 40551280, 2025). "During the acute phase of toxoplasmosis, the concomitant IL-10 and IL-4 responses dampen systemic type-1 cytokine production and prevent lethal immunopathology." (PMID 38029261, 2023). "Toxoplasmosis has a strong effect on the concentration of various cytokines, especially interleukin (IL)-10, IL-5, IL-6, and transforming growth factor beta (TGF-β)." (PMID 34583758, 2021). "IL-10 has proved to be important in the preservation of tissue integrity in several experimental models of infectious diseases, including toxoplasmosis." (PMID 25214715, 2014). "In the course of toxoplasmosis in patients, the level of IL-10 is five-fold higher than that in healthy controls; however, the levels of IL-12 and TNF-α are comparable to those observed in healthy controls." (PMID 24146978, 2013). "Chronic resistance to toxoplasmosis requires a delicate balance between pro-inflammatory cytokines like IFNγ and TNFα to control infection and regulatory cytokines like IL-10 to prevent immunopathology." (PMID 22479310, 2012). "Actually, IL-10 is known to play vital roles in the control of inflammatory responses during acute toxoplasmosis, and to inhibit tissue damage during the chronic phase." (PMID 22470449, 2012). "We found the level of IL-10 to be fivefold higher in the course of toxoplasmosis than in healthy controls." (PMID 19478959, 2009). "Toxoplasmosis is accompanied by the production of immunosuppressive lymphokines IL-10 and TGF-beta that can interfere with the process of immunization." (PMID 17916246, 2007). "In agreement with this hypothesis, NK cells are known to dampen immune responses to several pathogens by producing IL-10 during systemic infection in a toxoplasmosis model." (PMID 40661959, 2025). "IL-10 has a prominent role in the prevention of immune hyperactivity, and it inhibits the activity of Th1 cells, thus maintaining immune balance by reducing inflammatory reactions during toxoplasmosis." (PMID 37502604, 2023). "Indeed, several studies have demonstrated that IL-10 production secreted during toxoplasmosis decreased host resistance and increased parasite burden." (PMID 33013917, 2020). "The role of IL-10 in preventing immunopathology during toxoplasmosis is a topic of great interest." (PMID 28706518, 2017). "Although the AHR can contribute to Treg development and T cell IL-10 production, processes that constrain the immune response during toxoplasmosis, no deficiencies in these pathways were observed in infected Ahr-/- animals." (PMID 26010337, 2015). "Additionally, IL-21 has been associated with the differentiation of IL-10 producing CD4+ T cells, which contribute to limiting immune-mediated pathology during toxoplasmosis." (PMID 23667536, 2013). "It has been documented in animal models that the infection by T. gondii may trigger a fatal proinflammatory cytokine storm; in this context, its regulation, importantly mediated by IL-10 and TGF-β, has been implicated in preventing tissue destruction in several toxoplasmosis models." (PMID 32231666, 2020).
toxoplasmosis (continued). "In addition to IFN-γ, TNF-α, cerebral and ocular mRNA levels of IL-6, NOS2 and IL-10 are increased in the brain and eye of mice infected with T. gondii, and these molecules promote protection against toxoplasmosis while in the case of IL-10, this cytokine modulates susceptibility to disease –." (PMID 23990781, 2013). "Microglia were shown to secrete IL-10 and TGF-beta during toxoplasmosis which attenuated the inflammatory immune response and led to asymptomatic persistence of the infection." (PMID 27842570, 2016). "IL-10 is important in the context of toxoplasmosis to prevent excessive inflammation in TE, but given IL-10 is an anti-inflammatory cytokine, it would not necessarily be considered protective in a vaccine model." (PMID 36986434, 2023). "The results suggested that Th1-mediated cellular immunity in the group immunized with CAV-2-ROP18 is not dependent on IL-10 production during the cellular response against toxoplasmosis." (PMID 25886737, 2015). "Susceptibility to toxoplasmosis was not due to defective expression of IFN-γ, TNF-α, NOS2 or IL-6 in the retina and brain, differences in IL-10 expression in these organs or to impaired induction of T. gondii-reactive T cells." (PMID 23990781, 2013). "In toxoplasmosis, the pro-inflammatory process is counterbalanced by the simultaneous induction of critical, non-redundant counter-regulatory mediators, including IL-10 and LXs." (PMID 22693634, 2012). "In most anti-toxoplasmosis vaccine studies, Th2 cytokines were significantly induced, while a few studies observed no statistically significant production of IL-10, which could be explained if the aim was to achieve a better Th1 response." (PMID 40551280, 2025). "Notably, FoxP3- T-bet+ Th1 cells are thought to be the critical source of IL-10 during toxoplasmosis, but since previous studies have shown that the AHR is not expressed at detectable levels in Th1 cells it was unlikely that AHR activity would directly affect IL-10 production by this population." (PMID 26010337, 2015).
chlamydial infection (36 papers, 2008 to 2025). "During chlamydial infection, high IL-10 secretion was shown to be associated with pathogenesis in a mouse model of Chlamydia trachomatis (C. trachomatis) infection." (PMID 32326284, 2020). "Collectively, our data sheds light on the potential roles of these cytokines implicated during chlamydial infections, but more importantly, how IL-10 regulates Chlamydia inflammation via SOCS proteins." (PMID 32684836, 2020). "The higher expression of the IL-10 gene promoter has been associated with increased chlamydial infection and disease severity." (PMID 27219467, 2016). "During chlamydial infection, high IL10 production has been associated with pathogenesis in a mouse model of C. trachomatis infection." (PMID 23527290, 2013). "In case of ocular chlamydial infection, IL-10 has been shown to be associated with scarring and blindness." (PMID 18828896, 2008). "Polymorphisms in the human IL10 gene are associated with diminished T cell proliferation in response to chlamydial infection and with increased risk of tubal damage and infertility after chlamydial infection." (PMID 22844448, 2012). "Studies in animals have shown that a deficiency in the IFN-γ response, an overtly suppressive IL-10 response, or a delay in the development of a global T cell response during chlamydial infection can all lead to enhanced bacterial dissemination and disease sequelae." (PMID 21573182, 2011). "Therefore, increased IL-10 expression is not only associated with persistent chlamydial infection but may also be associated with complications of chlamydial infection, such as infertility." (PMID 36504792, 2022). "Evidence of uterine horn pathology and reduced IL-10 levels in the FGT of infected ISG15−/− mice further supports a critical dual function of ISG15 in controlling chlamydial infection and modulating the resulting inflammatory responses." (PMID 40627782, 2025). "In another study, the IL-10 level of patients with chlamydial infections was higher than that of uninfected individuals." (PMID 36504792, 2022). "The results suggest that Sema3E can modulate cytokine responses differently by preferentially promoting Th1/Th17 while reducing IL-4/IL-10 responses after chlamydial infection." (PMID 35983029, 2022). "Specifically, we have observed that Sema3E treatment enhances IFN-γ and IL-17 production but reduces IL-10 and IL-4 cytokine response in the lungs and spleen after chlamydial infection." (PMID 35983029, 2022). "The secretion of IFN-γ is not only regulated by IL-12, IL-18, IL-10, and other cytokines after chlamydial infection, but is also enhanced through a positive feedback mechanism." (PMID 34093528, 2021). "Interleukin 10 (IL-10) is an anti-inflammatory factor produced during chlamydial infection, while dendritic cells (DCs) are powerful antigen-presenting cells that induce a primary immune response in the host." (PMID 34093535, 2021). "The immunopathology of chlamydial diseases is exacerbated by a broad-spectrum of inflammatory mediators, which we reported are inhibited by IL-10 in macrophages." (PMID 32684836, 2020). "It appears that the Th1 CD4 cell response plays a dominant role in protective immunity, while Th2 CD4 cytokines (particularly IL-10) play a role in the immunopathology of chlamydial infection." (PMID 32326284, 2020). "In our results, the expression of IL-4 and IL-10 were increased significantly in the coinfection groups, suggesting that chlamydial infection mediated the polarization of Th1/Th2 to the Th2 direction." (PMID 32326284, 2020). "Transcriptomic and proteomic profiling of the macrophage response to chlamydial infection highlighted the role of the type I interferon and interleukin 10-mediated responses." (PMID 28440293, 2017). "On average, IL10 mRNA expression levels were observed to be higher (P<0.05) than TNFα mRNA expression levels in Group I animals (with current chlamydial disease)." (PMID 23527290, 2013).
chlamydial infection (continued). "Although high levels of variability was observed within each group, there was a significantly high expression (P<0.05) of TNFα and IL10 mRNA in animals with current chlamydial disease when compared to the remaining animals in the study." (PMID 23527290, 2013). "In the studies in other hosts, an increase in IL10 production corresponded with a decrease in interferon-gamma (IFNγ) production, which is the principle Th1 cytokine that provides protection against chlamydial infection." (PMID 23527290, 2013). "Though not significant, these neonates also presented with elevated IL-2, IL-10, and IL-13 when compared to adult mice, showing that chlamydial infection alone was enough to elicit a Th2-like response." (PMID 24376704, 2013). "In a preliminary study to evaluate the role of these cytokines in koala chlamydial infections and disease, TNFα and IL10 responses of koala PBMCs, isolated from three cohorts of koalas was measured." (PMID 23527290, 2013). "It has been reported that endogenously produced IL-10 differentially regulates chlamydial infections among inbred mouse strains." (PMID 22529524, 2012). "In the C3−/− mice the lung tissue concentrations of IFN-γ and TNF-α, two key cytokines in the defense against chlamydia, and of IL-6 and IL-10, were either similar to or even higher than for WT controls." (PMID 23189195, 2012). "In an attempt to mimic chronic chlamydial infections, Macaca nemestrina fallopian tubes received repeated C. trachomatis infections, which resulted in fibrosis and elevated IL-6, IL-10, IL-2, and IFNγ levels." (PMID 22894815, 2012). "IL-10 producing cDCs following chlamydial infection of the lung have been shown to reduce allergen-specific cytokine production and CD4+ T cell responses." (PMID 21079691, 2010). "Given that it has been reported that IL10−/− mice display enhanced immunity to chlamydial infection, we asked if the LGT compartment was dominated by Th1 effector cells rather than Th2 cells, as seen in WT mice." (PMID 21079691, 2010). "In murine models of chlamydial infection, high levels of IL-10 impede pathogen clearance, whereas IL-10 mutant mice clear infection faster than genetically intact controls." (PMID 19397832, 2009). "Furthermore, C. psittaci infection suppresses host immunity and exacerbates the risk of secondary infection by impairing macrophage function and promoting the interleukin 10 (IL-10) expression, contributing to chlamydial infection and immune evasion." (PMID 41000381, 2025). "As a result, targeting IL-10 pathways could be considered as a way to enhance vaccine effectiveness, potentially leading to better control of chlamydial infections, as has been suggested by other authors." (PMID 39199857, 2024). "Relevant KO mice, siRNA/chemical inhibition, or antibody blockade may be used for identifying the exact mechanism of IL-10 in chlamydial infection." (PMID 36504792, 2022). "The functions of IL-10 in chlamydial infection are however more complex." (PMID 34093528, 2021). "In addition to findings about changes in expression and the possible roles of IL-10 in chlamydial infection, some deeper insights into the roles of IL-10 were gained." (PMID 34093528, 2021). "To explore the mechanisms by which IL-13 mediates the host response to Cmu lung infection, we determined whether IL-13 influences the expression of IFN-γ and IL-10, factors known to play a central role in the immune response to chlamydial infection." (PMID 21573182, 2011). "However, the function of IL-10 in the persistence of chlamydial infections remains inadequately understood, and the possibility of therapeutically inhibiting IL-10 to amplify anti-chlamydial immunity and improve vaccine effectiveness has yet to be explored in the context of animal chlamydiosis." (PMID 39199857, 2024).
chlamydial infection (continued). "CD8 T cells have conflicting roles in chlamydial infections, having been shown to cause immunopathology, predominantly through the production of TNFα, but in some cases also protection through atypical Chlamydia-specific cells secreting IL13 in addition to TNFα, IFNγ, and IL10." (PMID 36799886, 2023). "Furthermore, attempting to use the corresponding antibody or inhibitor of IL-10 to control chlamydial infection may be beneficial." (PMID 36504792, 2022). "In contrast, the TLR3-/- mice secreted higher levels of IL-10, TNF-α and IFN-γ than wild-type mice at day 7 of infection, suggesting that TLR3 deficiency did not result in a global downregulation in synthesis of cytokines during early stages of chlamydial infection." (PMID 29624589, 2018). "Resistance to chlamydial infection is associated with increases in Th1 cytokines, such as IFNγ, which promote cytotoxic T cell responses; conversely, a Th2-dominated response, characterised by increased IL4 and promoted by IL10, is associated with persistence of infection." (PMID 27706211, 2016). "We also assessed the systemic response by splenic T cells expressing cytokines with known importance to resolution of chlamydial infections and pathology; IFNγ, TNFα, IL17, IL13, IL10." (PMID 36799886, 2023). "Within koalas with current chlamydial disease, significantly higher expression of IL-10 is detected in PBMCs compared to koalas with asymptomatic chlamydial infection and no chlamydial infection/disease." (PMID 33546104, 2021). "In particular, in infections of intracellular bacteria which often bias a Th1-like response, such as chlamydia, B cells may more likely modulate immune responses through IFNγ, rather than IL-10 production." (PMID 37759658, 2023). "In addition, we found that women with a single chlamydial infection (CT-P) had slightly higher vaginal IL-10 levels, although not significantly different." (PMID 29404279, 2018). "In preliminary studies comparing wild koalas with overt chlamydial disease, previous evidence of C. pecorum infection or no signs of C. pecorum infection, we revealed strong but variable expression of TNFα and IL10 in wild koalas with current signs of chlamydiosis." (PMID 23527290, 2013). "Notably, granulomas were absent following chlamydial infection of IL-10 knockout mice which had a more dominant TH1 type immune cell response than wild-type mice." (PMID 20011598, 2009). "Chlamydial infection of mice lead to the development of CD4+ T cells that significantly secreted IL-6, IL-10, and GM-CSF, but not IL-4, in response to C. muridarum re-stimulation." (PMID 18700040, 2008). "qPCR was used to examine mRNA expression for Th1 (IFNγ), Th2-promoting (IL6, IL10) and Th17 (IL17A) cytokines, along with CD4 and CD8 in whole blood of koalas (n = 74) from Mt Eccles and Raymond Island in Victoria, Australia, with and without natural chlamydial infection." (PMID 31371797, 2019).